ITGB1 (integrin subunit beta 1)
Diseases named in the same sentence as ITGB1 in open-access papers (continued):
Sharing a sentence is not in itself a finding about the gene and the disease.
reovirus infection (1 paper, 2018). "Previous studies have shown that reovirus infection in ITGB1-deficient mice is not prevented, but rather results in low levels of infection." (PMID 30326628, 2018).
Right ventricular hypertrophy (1 paper, 2024). In this case the right ventricle is more muscular than normal, causing a characteristic boot-shaped (coeur-en-sabot) appearance as seen on anterior- posterior chest x-rays. "Histological studies confirmed Exo-ITGB1's prevention of right ventricular hypertrophy and pulmonary artery remodeling." (PMID 38767703, 2024).
sarcopenia (1 paper, 2025). Progressive decline in muscle mass due to aging which results in decreased functional capacity of muscles. "Of note, decorin alleviated skeletal muscle fibrosis and atrophy in D‐gal–induced aged mice and NOR‐10 cells by activating the ITGB1/Akt/mTOR signalling pathway, which suggests that decorin supplementation may be a potent therapeutic strategy to combat age‐associated sarcopenia." (PMID 41350105, 2025).
SARS-CoV infections (1 paper, 2022). "It was found that 45.87% of the associated genes (CASP3, CASP9, MAPK1, MAPK3, XIAP) contributed to cytochrome C-mediated apoptotic response and 3.67% of the associated genes (BECN1, FXYD2, GSK3B, HSP90AA1, ITGB1, MAP1LC3B) contributed to SARS-CoV infections." (PMID 36164436, 2022).
serous ovarian carcinoma (1 paper, 2025). "To elucidate the post-transcriptional mechanisms contributing to the differential expression of prognostic genes identified in Section 3.1, we next investigated microRNAs (miRNAs) that may regulate TIMP3, BRAF, and ITGB1 in high grade serous ovarian cancer (HGSOC)." (PMID 41294900, 2025). "The target genes analyzed in this study (e.g., ITGB1, TIMP3, and BRAF) were selected based on their strong prognostic relevance identified from cBioPortal survival analyses of high-grade serous ovarian carcinoma." (PMID 41294900, 2025).
spina bifida (1 paper, 2019). A congenital neural tube defect in which vertebrae are not fully formed. "ITGB1 has been associated with NTD through a knock‐in mouse showing an exencephaly and spina bifida (Ohyama, Kawano & Kawamura, 1997)." (PMID 30415495, 2019).
steatosis (1 paper, 2021). Increased lipid within the cytoplasm of cells. "We concluded that HSPD1/MMP14/ITGB1/miR-6881-5P/Lnc-SPARCL1-1:2 panel expression has a potential in the diagnosis of NASH, and also in differentiation between NAFLD without steatosis, NAFLD with simple steatosis and NASH." (PMID 34572434, 2021).
Telangiectasia (1 paper, 2025). Telangiectasias refer to small dilated blood vessels located near the surface of the skin or mucous membranes, measuring between 0.5 and 1 millimeter in diameter. "Another study used telangiectasia cell (TC)-derived exosomes modified by ITGB1 and enriched with miR-429-3p." (PMID 40868164, 2025).
tuberculosis (1 paper, 2024). A chronic, recurrent infection caused by the bacterium Mycobacterium tuberculosis. "The THBS signaling pathway is widely present in the region enriched with macrophages in the tuberculosis spot, indicating that macrophages and fibroblasts interact depending on THBS1/2-CD36/SDC4/ITGA3/ITGB1, which may be a key pathway for tuberculosis progression." (PMID 39431015, 2024).
Ureteral obstruction (1 paper, 2023). Obstruction of the flow of urine through the ureter. "Here, the aim of our study was to investigate the dysregulate expression of lncRNA MALAT1 in TGF-β1 treated HK2/NRK-49F cells and unilateral ureteral obstruction (UUO) mice model, defining its effects on HK2/NRK-49F cells and UUO mice fibrosis process through the miR-124-3p/ITGB1 signaling axis." (PMID 37872392, 2023).
Vestibular schwannoma (1 paper, 2025). A vestibular schwannoma (also known as acoustic neuroma, acoustic neurinoma, or acoustic neurilemoma) is a benign, usually slow-growing tumor that develops from the VIIIth cranial nerve supplying the inner ear. "Our cell communication analysis based on the curated receptor-ligand pair database showed that fibroblast in vestibular schwannoma microenvironment mainly regulated the biological behavior of tumor cells through PSAP/GPR37L1, MDK/(ITGA6 + ITGB1), IGF2/(ITGA6 + ) and MDK/LRP1 signaling axes." (PMID 40629113, 2025).
tumor (452 papers, 2006 to 2026). "Tumoral ITGB1 facilitated the establishment of pro-tumorigenic TME by orchestrating tumor-associated myeloid populations." (PMID 41632816, 2026). "In vivo xenograft models further validate these findings: FBXO6 overexpression reduces tumor growth, Ki67 levels, and ITGB1-associated signaling." (PMID 41857001, 2026). "Ligand-receptor pairs linked to high-risk tumors, including IL1A_IL1RAP, COL5A1_ITGB1, APP_NCSTN, PLAU_ITGA5, AGRN_ITGB1, and LAMC2_ITGA6, were found to be particularly enriched in tumor regions." (PMID 40021759, 2025). "The available literature indicates correlations between ITGB1 expression and CC tumor stage, grade, and HPV-related risk." (PMID 41148856, 2025). "Mechanistically, ENO1 regulated CD8+ T cell function and tumor-associated macrophage (TAM) polarization via the SPP1-ITGA4/ITGB1 pathway in the TME." (PMID 40665335, 2025). "The different mechanisms underlying ITGB1-mediated primary and adaptive drug resistance are associated with a particular tumor type or the mode of action of a given medication." (PMID 38279122, 2024). "Through connectivity analysis on different cell-type-specific networks, we can deconvolve prognostic signatures into cell types and found that the prognostic effects of ITGB1 are linked to CAF-mediated tumor progression." (PMID 38347596, 2024). "We found that patients with low ITGB1 expression had a significantly high tumor mutation burden (p = 0.006)." (PMID 35864742, 2023). "By enrichment analysis of ITGB1 differentially expressed molecules, we found that in addition to being associated with tumor adhesion, ITGB1 was also significantly associated with tumor immune and metabolism." (PMID 37007126, 2023). "Positive ITGB1 staining was also associated with the depth of tumor invasion (p = 0.017) and clinical stage (p = 0.011)." (PMID 35864742, 2023). "In summary, ITGB1 was associated with worse prognosis and regulated tumor metabolism and cuproptosis in DGC." (PMID 37007126, 2023). "The ITGB1-blocking antibody reduced the tumor metastasis caused by ALKBH5 overexpression and diminished lymphatic tube formation, EOC cell migration, and invasion." (PMID 36632222, 2023). "Through enrichment analysis, we found that ITGB1 was associated with tumor metabolism and immune regulation." (PMID 37007126, 2023). "FN1 and ITGB1 also affect Overall survival rate, immune cell infiltration, tumor mutation burden and microsatellite instability in pan-cancer." (PMID 35979350, 2022). "Noteworthy, YWHAZ, which is a central hub protein regulating multiple biological processes, was also predicted to be implicated in ITGB1-mediated HCC tumor growth, based on our comprehensive analysis." (PMID 34977001, 2021). "Motivated by prior results implicating that ITGB1 expression was notably increased in HCC tumor tissues, we sought to elucidate the mechanism underlying the overexpression of ITGB1." (PMID 34977001, 2021). "It has been widely reported that over-expression of ITGB1 is associated with tumor growth, metastasis and drug resistance via downstream signaling pathways in various cancers." (PMID 27966454, 2017). "Angiopoietin-2 ameliorated the dormancy of ER+ tumor cells in BM endothelial niche and promoted their survival under estrogen deficiency via integrin &1 (ITGB1)." (PMID 27353038, 2016). "For example, sialylation of ITGB1 has been linked to increased chemoresistance in tumor cells." (PMID 39937175, 2025). "The expression of Piezo1 and ITGB1 was also associated with tumor size and number." (PMID 40667648, 2025). "In fact, SEMA7A may increase the polarization of tumor-associated macrophages (TAMs) toward the M2 phenotype in an ITGB1-dependent manner." (PMID 41019072, 2025). "Albeit different environments, it is plausible to hypothesize that a similar mechanism could occur in the TME, where Itgb1 is known to be expressed by tumor-associated macrophages (TAMs)." (PMID 39272810, 2024).
tumor (continued). "This study discovered that ITGB1 expression was adversely correlated with immune/stromal/ESTIMATE scores in SARC, indicating that ITGB1 was negatively correlated with immunological tolerance, potentially through tumor-associated macrophage contact with T cells." (PMID 38402311, 2024). "ITGB1 studies in cancer have so far been restricted to a particular cancer species; Therefore, ITGB1 must be subjected to a pan-cancer analysis in order to better understand its interactions with the underlying molecular mechanisms of action and the tumor immune microenvironment." (PMID 38402311, 2024). "ITGB1 is one of the most common genes that associated with adhesion in the tumor." (PMID 37007126, 2023). "The results showed that ITGB1 expression was positively associated with pathology G-stage and tumor T-stage, which indicating that ITGB1 may promote GC progression." (PMID 37667169, 2023). "In addition, higher expression of ITGB1 was associated with worse pathological G-staging and tumor T-staging, which suggested that ITGB1 is a risk factor for poor prognosis in GC." (PMID 37667169, 2023). "ITGB1 gene encodes Integrin beta-1 surface receptor that are involved in cell proliferation, cell adhesion and recognition as well as metastatic diffusion of tumor cells." (PMID 35399006, 2022). "Considering the tumor heterogeneity of the patients and the association of ITGB1 with cancer stemness properties, certain tumor subpopulations might not have significant high expression of ITGB1." (PMID 36186483, 2022). "Importantly, the requirement for CDC42 activity in TEM and metastasis is linked to the CDC42-dependent induction of the ITGB1 gene, with β1 integrin playing a critical role in tumour cell intercalation into the endothelium." (PMID 34374417, 2021). "Moreover, we further disclosed the underlying of collagen/ITGB1 induced tumor progression, which was dependent on a BCL9L/β-catenin/BCL2 signaling pathway." (PMID 34319913, 2021). "ITGB1 was chosen for further study based on its association with the tumour ECM." (PMID 33613118, 2021). "Genes encoding for integrins (such as ITGAV, ITGBL1, and ITGB1) that can promote tumor cell proliferation and migration and genes related to the Hippo signaling pathway, one of the signaling pathways which has been implicated in cancer by promoting cell proliferation, were also downregulated." (PMID 32616706, 2020). "The protein encoded by ITGB1 (Integrin beta-1) is a membrane receptor involved in cell adhesion and recognition in a variety of processes, including embryogenesis, hemostasis, tissue repair, the immune response and metastatic diffusion of tumor cells." (PMID 31578316, 2019). "Thus, we propose that the prognostic effects of ITGB1 are linked to CAF-mediated tumor progression." (PMID 38347596, 2024). "ITGB1 encodes the β1 subunit of integrin which is a membrane receptor that regulates cell adhesion and recognition and is involved in many important cellular biological processes such as embryogenesis, hemostasis, tissue repair, immune response, and metastasis of tumor cells." (PMID 38292328, 2024). "Mechanistically, FF-derived FN activates the ITGB1/FAK-SRC signaling pathway to promote tumor cell motility and colonization." (PMID 41511363, 2026). "Additional rescue experiments show that FBXO6 counteracts the tumor-promoting effects of ITGB1 overexpression." (PMID 41857001, 2026). "In contrast, the tumor metastasis signals in the NGR-ALKBH5-siRNA-BNVs + ITGB1 group were partially restored." (PMID 40585991, 2025). "To validate the observed accumulation of integrins on the tumor cell surface, we focused on the most enriched integrins upon AP2 loss, namely ITGB1, ITGB6, ITGA2, and ITGA3." (PMID 40050266, 2025). "Functionally, COL10A1 contributes to ECM remodeling and can interact with proteins such as prolyl 4-hydroxylase subunit beta (P4HB) and integrin subunit beta 1 (ITGB1) to facilitate tumor cell proliferation and metastasis." (PMID 40826474, 2025).
tumor (continued). "The Piezo1/ITGB1 axis forms a positive feedback loop with matrix stiffness, amplifying the mechanosensory capacity of tumor cells and promoting their proliferation and progression." (PMID 40667648, 2025). "These tumor subtypes cooperatively drive CD8+ T cell exhaustion through the MDK–(ITGA4+ITGB1), MIF–(CD74+CXCR4), and TGF-β signaling pathways." (PMID 40948762, 2025). "We analyzed the correlation of FN1, ITGA4, ITGA5, ITGAV, ITGB1, ITGB3 and ITGB6 with disease status, risk of tumor recurrence according to the 2015 American Thyroid Association guidelines, and patient outcome." (PMID 40423510, 2025). "ALKBH5 is an RNA demethylase enzyme that, upon inhibition, reduces the m6A modification levels in tumor cells, thereby affecting ITGB1 expression and inhibiting tumor cell proliferation and metastasis." (PMID 40585991, 2025). "The transmembrane glycoprotein signaling receptor ITGB1 mediates the tumor-promoting effects of ECM stiffness by transmitting mechanical signals." (PMID 40685383, 2025). "Functional studies showed that secreted FABP4 augmented HCC tumor growth by modulating the PI3K/AKT/β-catenin signaling pathway through its interaction with ITGB1." (PMID 41392988, 2025). "In vitro assays revealed that HUVEC cells exhibited elevated levels of SOX18, ITGA5, and ITGB1 compared to tumor cells and CAFs." (PMID 39823457, 2025). "This study identifies COL1A1, ITGB1, THY1, and PDGFRA as crucial regulators of UCEC progression, with altered expression linked to tumor behavior and patient survival." (PMID 40817072, 2025). "ITGA5 and ITGB1 (αV and β1 integrins) mediate cell adhesion and promote survival, proliferation, and migration of tumor cells, thus contributing to tumor progression and metastasis." (PMID 40965626, 2025). "Compared to IgG treatment, the expression of c‐Jun in Schwann cells and p‐FAK in tumor cells were attenuated in KPC mice upon anti‐ITGB1 treatment." (PMID 40923379, 2025). "Interactions with tissue stem cells through the Col1a1/Cd93, Col1a1/Itga5, Fn1/Plaur and Itgb1/Vcan pathways underscore the critical role of the monocyte-macrophage system in tumour immunosurveillance and immunomodulation." (PMID 40046334, 2025). "Consistently, therapeutic blockade of ITGB1 using neutralizing antibody synergized with gemcitabine, yielding superior tumor suppression." (PMID 40923379, 2025). "The in vivo validation using subcutaneous xenografts demonstrated that sorafenib significantly reduced tumor volume and weight under ITGB1 silencing compared to controls, with parallel suppression of Ki67+ proliferative cells." (PMID 40685383, 2025). "JUN/FOS regulate proliferation, differentiation, apoptosis, and inflammation, with aberrant activation promoting tumor growth and invasion, while ITGB1 critically mediates cell adhesion, migration, and signaling." (PMID 40725477, 2025). "Our in vivo observations also showed that suppression of ITGB1 mitigated the effect of rhFABP4-induced HCC tumor growth." (PMID 41392988, 2025). "Identifying key signaling pathways and ligand-receptor pairs, such as PSAP-GPR37 and SPP1-(ITGA5+ITGB1), highlights the importance of intercellular communication in modulating tumor behavior." (PMID 39949776, 2025). "These molecules are directly connected to the ECM and the immune microenvironment, suggesting a complex interplay between the Piezo1/ITGB1 axis and the tumor microenvironment." (PMID 40667648, 2025). "As monitored by Incucyte time-lapse imaging of clustering, among all tested gene modulations, ITGB1-KO in Jurkat cells via 2 separate sgRNAs showed the strongest inhibition of heterotypic T tumor cell interactions with differences present as early as 3 hours." (PMID 40955669, 2025). "The results showed a significant reduction in tumor growth in the ITGA5/ITGB1 double-knockdown group, indicating that these integrins contribute to OC progression." (PMID 40770810, 2025).